SOST (sclerostin)
Description:
Negative regulator of bone growth that acts through inhibition of Wnt signaling and bone formation.
Synonyms: VBCH; DAND6; CDD; SOST1
Tractability: Small molecule: a high-quality ligand is known. Antibody: an approved drug acts on it; UniProt places it where antibodies can reach, with high confidence; its Gene Ontology location is reachable by antibodies, with high confidence; UniProt predicts a signal peptide or a membrane-spanning region. PROTAC: a small molecule that binds it is known.
Gene: Protein-coding gene on chromosome 17 (43,753,738 to 43,758,791, reverse strand). Ensembl gene ENSG00000167941.
Subcellular location: Secreted, extracellular space, extracellular matrix
Pathways (Reactome):
Signal Transduction: Negative regulation of TCF-dependent signaling by WNT ligand antagonists; TCF dependent signaling in response to WNT
Gene Ontology:
Molecular function: carbohydrate binding; DNA-binding transcription factor binding; molecular function inhibitor activity; protein binding; BMP binding
Biological process: cellular response to parathyroid hormone stimulus; negative regulation of BMP signaling pathway; negative regulation of canonical Wnt signaling pathway; negative regulation of protein-containing complex assembly; positive regulation of DNA-templated transcription; response to mechanical stimulus; negative regulation of ossification; negative regulation of Wnt signaling pathway; ossification
Cellular component: extracellular region; Golgi apparatus; protein-containing complex
Genetic constraint (gnomAD): Loss-of-function variants: 14 observed, 13.23 expected, observed/expected ratio (o/e) 1.06, 90% interval 0.7 to 1.63. The synonymous counts are far from expectation, so gnomAD's model fits this gene poorly and the ratio says little. Missense variants: 291 observed, 266.28 expected, observed/expected ratio (o/e) 1.09, 90% interval 0.99 to 1.2. Synonymous variants: 150 observed, 117.31 expected, observed/expected ratio (o/e) 1.28, 90% interval 1.12 to 1.46.
Homologues: Orthologues: chimpanzee SOST (99% identical), macaque SOST (98% identical), dog SOST (97% identical), pig SOST (93% identical), rabbit SOST (93% identical), rat Sost (90% identical), mouse Sost (87% identical), guinea pig SOST (72% identical), zebrafish sost (50% identical). Paralogues in human: SOSTDC1 (37% identical).
Diseases named in the same sentence as SOST in open-access papers:
SOST is named in the same sentence as 284 diseases in open-access papers, as found by Europe PMC text mining. Sharing a sentence is not in itself a finding about the gene and the disease. The quoted sentences say what the papers report.
osteoporosis (412 papers, 2010 to 2026). A condition of reduced bone mass, with decreased cortical thickness and a decrease in the number and size of the trabeculae of cancellous bone (but normal chemical composition), resulting in increased fracture incidence. "This study aimed to investigate the associations between serum sclerostin levels, sarcopenia, and osteoporosis in older women." (PMID 41594249, 2026). "This study aimed to investigate the association between circulating sclerostin levels and the coexistence of sarcopenia and osteoporosis in community-dwelling older women." (PMID 41594249, 2026). "Here we show that nine circulating proteins associate with forearm fracture risk, including sclerostin and osteoprotegerin targeted by existing osteoporosis treatments, and three other known bone-related proteins, providing proof of concept for our MRpipeline." (PMID 41723149, 2026). "The humanized anti-sclerostin monoclonal antibody, romosozumab, was first and commercially launched on the Japanese market for the therapy of osteoporosis in patients at high risk of fracture in March 2019 (Amgen Astellas BioPharma Release)." (PMID 40429697, 2025). "We demonstrated that bisphosphonates, PTH analogs, denosumab, and sclerostin inhibitors can reduce clinical fracture risk in CKD patient’s osteoporosis but with low to very low confidence of evidence." (PMID 40599806, 2025). "Numerous researchers have focused on evaluating the clinical relevance of sclerostin in relation to osteoporosis and its potential role in predicting fracture risk." (PMID 41367909, 2025). "The treatment with recombinant PTH (teriparatide) or the sclerostin inhibitor (romosozumab) is reserved for patients with osteoporosis at very high risk for fracture." (PMID 41393738, 2025). "A large number of studies have revealed that sclerostin is elevated in T1D and T2D, and diabetic patients are more susceptible to osteoporosis." (PMID 39720253, 2024). "Pathogenesis of bone loss depending on the circulatingserum sclerostin levels and osteoporosis risk is of great clinical relevance." (PMID 38352898, 2024). "In humans, mutations in the SOST gene are strongly linked to osteoporosis, particularly in postmenopausal women." (PMID 39596516, 2024). "Sclerostin inhibits canonical Wnt signaling, which is important for the bone formation activity of osteoblasts, and elevated sclerostin has been implicated in adult osteoporosis." (PMID 39062269, 2024). "Sclerostin (SCL), encoded by SOST gene, is a negative regulator of bone formation and its neutralizing antibody is effective in reducing the incidence of osteoporosis." (PMID 39066929, 2024). "Romosozumab, a monoclonal antibody that inhibits sclerostin, was first approved for clinical use in Japan in 2019 for the treatment of high-fracture-risk osteoporosis." (PMID 39767786, 2024). "Romosozumab, a monoclonal antibody that targets sclerostin, has been approved for the treatment of high-risk osteoporosis." (PMID 39104397, 2024). "Based on this, this article reviews the clinical evidence regarding serum sclerostin in diabetes and osteoporosis, and delve into the underlying mechanisms involved." (PMID 39720253, 2024). "In patients with osteopenia and osteoporosis, decreased sclerostin levels were associated with an increaseddisease risk." (PMID 38352898, 2024). "Sclerostin has been previously associated with bone loss in conditions related to immobilization, and anti-Sclerostin therapy has been proposed for osteoporosis or other bone diseases characterized by bone loss." (PMID 39125464, 2024). "It is worth noting that a commercial sclerostin antibody (romosozumab) had been approved for the treatment of osteoporosis in postmenopausal women with a high risk of fracture in 2019." (PMID 39342093, 2024).
osteoporosis (continued). "Conversely, other studies suggest a negative association between serum sclerostin levels and BMD, with elevated circulating sclerostin levels identified as a strong and independent risk factor for osteoporosis-related fractures in postmenopausal women." (PMID 38474734, 2024). "The upregulation of sclerostin and Dkk1 is thought to hinder bone formation, thereby exacerbating the risk of osteoporosis and fragility fractures in RA patients." (PMID 38022514, 2023). "Currently, a humanized monoclonal anti-sclerostin antibody, is being used in the clinical practice for the treatment of osteoporosis and high fracture risk." (PMID 37919715, 2023). "Studies have reported an association with altered SOST expression and changes in the bone mineral density in individuals, particularly with single-nucleotide polymorphisms (SNPs) at the SOST promotor, leading to lower bone density and osteoporosis." (PMID 37047469, 2023). "Because lower levels of DKK-1 and SOST were found in AS patients, the authors suggested that the main cause of osteoporosis in AS should be searched for in other alterations such as immobilization, systemic inflammation, and biomechanical factors." (PMID 37887030, 2023). "Circulating sclerostin level is significantly higher in diabetic persons, which inhibits the function of osteoblasts and bone formation, thus increasing the risk of osteoporosis." (PMID 37033244, 2023). "While much has been learned about the role of anti-sclerostin therapy in the setting of quantitative bone loss in osteoporosis and multiple myeloma, the role of sclerostin in wear-induced PPOL has yet to be elucidated." (PMID 36550970, 2022). "It was also found that siRNA LNPs can enter bone cells after intravenous injection to induce the gene silencing of SOST encoding sclerostin, providing a new possibility for the treatment of osteoporosis." (PMID 35269550, 2022). "Additional genes whose polymorphisms and mutations have been related to osteoporosis comprise: (i) Sclerostin (SOST), whose polymorphisms have been associated with some parameters of osteoporosis, such as B bone mineral density or risk fracture." (PMID 35163424, 2022). "Unlike previously published studies, our study was performed in a general fracture population and did not only investigate the association of serum sclerostin with bone mineral density but also with the diagnosis osteoporosis." (PMID 35705746, 2022). "Regarding sclerostin as a biomarker for bones, high levels of sclerostin have been detected in patients with thalassemia-associated osteoporosis and abnormal bone remodeling in myeloma." (PMID 36506070, 2022). "It is a humanized monoclonal antibody against sclerostin that is currently being used in clinical practice for the treatment of osteoporosis and high risk of fracture." (PMID 35805996, 2022). "Association with SOST, which provides the genetic basis of romosozumab, a recently developed osteoporosis medication, was also detected." (PMID 36225206, 2022). "Bone mineral density was positively associated with sclerostin levels (r = 0.17, p = 0.026) and patients with osteoporosis had a significantly lower serum sclerostin compared to non-osteoporotic fracture patients (mean 41.9 pmol/L vs 48.1 pmol/L; p = 0.03)." (PMID 35705746, 2022). "This prompted the development of a humanised monoclonal antibody (Romozumab) against SOST which is now an osteo-anabolic osteoporosis therapeutic that reduces fracture risk." (PMID 35057801, 2022). "Sclerostin was shown to suppress bone formation, and romosozumab, an antisclerostin antibody, was approved for the treatment of osteoporosis in postmenopausal women at high risk of bone fractures." (PMID 35805996, 2022). "It has also been linked to the presence of sclerostin, a wingless-type mouse mammary virus-integration site pathway, which is currently being used as a target for some osteoporosis medications." (PMID 35573562, 2022).
osteoporosis (continued). "Sclerostin secreted by osteocytes serves as a mediator of mechanotransduction, characterized by the significant enhancement of the serum levels of sclerostin in patients with disused osteoporosis caused by unloading." (PMID 35562828, 2022). "Recently, the human SOST monoclonal antibody (romosozumab) has been approved for the treatment of osteoporosis in postmenopausal women at high risk for fracture." (PMID 34250013, 2021). "The increase in BMD in Sost−/− mice and in humans with decreased SOST function has led to consideration of sclerostin as a potential target for treatment of osteoporosis and other diseases associated with low bone mineral density." (PMID 34502021, 2021). "Romosozumab, a humanized monoclonal antibody specific for sclerostin (SOST), has been approved for treatment of postmenopausal women with osteoporosis at a high risk for fracture." (PMID 34502021, 2021). "Osteoporosis in cholestatic liver disease is associated with impaired bone formation, increased bilirubin and sclerostin, and lower insulin-like growth factor-1." (PMID 33807573, 2021). "Sclerostin’s anabolic function and as a possible therapeutic for osteoporosis, is based on the high bone mass phenotype in patients of sclerosteosis with a genetic deficiency of sclerostin." (PMID 33805567, 2021). "Romosozumab, a humanized anti-sclerostin monoclonal antibody designed for subcutaneous administration, was approved for the treatment of severe osteoporosis and postmenopausal women at high risk for osteoporotic fracture." (PMID 34361085, 2021). "The sclerostin antibody has been suggested to be an effective treatment option for WNT1 mutation-related osteoporosis." (PMID 32733380, 2020). "Romosozumab, approved by the FDA in 2019, is a humanized sclerostin-neutralizing antibody (Scl-Ab) indicated in postmenopausal women with osteoporosis at high risk for fracture." (PMID 33004873, 2020). "For example, single nucleotide polymorphisms in Wnt, β-catenin, and inhibitor sclerostin (SOST) are correlated with the development of human osteoporosis." (PMID 32664681, 2020). "Given the effectiveness of anti-sclerostin antibodies in reducing fracture risk in osteoporosis, trials have been initiated in other bone diseases." (PMID 33114755, 2020). "In osteoporosis, one of the most prevalent bone diseases worldwide, a monoclonal antibody inhibiting sclerostin known as romosozumab, was shown to reduce the risk for vertebral fractures in postmenopausal women within a 12 months period." (PMID 31752267, 2019). "Our study showed a strong association between bone mineral density and polymorphisms in the FDPS gene, and a borderline association with LRP5 and SOST polymorphisms in postmenopausal Romanian women with osteoporosis." (PMID 31774873, 2019). "Evidence interface provides the literature which supports the association of SOST gene with osteoporosis." (PMID 31086734, 2019). "Increased expression of the osteocyte-derived bone inhibitor sclerostin has been linked to estrogen deficiency-induced osteoporosis and is therefore a promising target for osteoporosis management." (PMID 30366476, 2018). "Three of these genes, RANKL, ADAMTS and SOST, were known to be associated with osteoporosis in humans, which makes them good candidate genes for osteoporosis in chickens." (PMID 28383518, 2017). "Together with the structure–function relationship derived from affinity maturation these new data will foster the rational design of new and highly efficient anti-sclerostin antibodies for the therapy of bone loss diseases such as osteoporosis." (PMID 27558933, 2016). "SOST has become an attractive target for the treatment of osteoporosis and other skeletal diseases associated with low bone mineral density and increased fracture risk." (PMID 26071314, 2015). "The polymorphisms of a number of genes, including vitamin D receptor, estrogen receptor α, estrogen receptor β, LRP5 and SOST, are associated with a risk of developing osteoporosis." (PMID 25815782, 2015).
osteoporosis (continued). "This is somewhat illustrated by results from our model, which underscore the decisive influence of osteocytes and the potential for sclerostin-targeted treatments to reduce bone loss in pathologic conditions ranging from osteoporosis to osteolytic cancers." (PMID 23717504, 2013). "High circulating levels of sclerostin have been associated with osteoporosis, Paget's disease, and metastatic bone disease." (PMID 23717504, 2013). "This led to a number of recent studies utilizing Sclerostin-neutralizing antibodies in animals and humans showing that neutralization of Sclerostin can restore bone density in osteoporosis models or other conditions resulting in bone loss." (PMID 24312339, 2013). "Overall, authors of systematic reviews and meta-analyses have concluded there is little conclusive evidence to support the use of these biomarkers in diagnosis or risk assessment for osteoporosis, a conclusion consistent with our findings with the possible exception of sclerostin in men." (PMID 41050357, 2025). "While ROMO effectively inhibits SOST by targeting both loops and demonstrates substantial anti-osteoporosis benefits, this broad inhibition may elevate the risk of cardiovascular side effects." (PMID 41403949, 2025). "Specifically, sclerostin expression is downregulated by mechanical loading, a process that promotes bone formation, whereas conditions such as physical inactivity, aging and osteoporosis are associated with elevated sclerostin levels, contributing to bone loss." (PMID 41159395, 2025). "In recent decades, parathyroid hormone-related analogues (e.g., teriparatide and abaloparatide) and anti-sclerostin agents (e.g., romosozumab) have also been tested as anabolic therapies for osteoporosis, especially in individuals who are at high risk of fragility fractures." (PMID 41369394, 2025). "Given the role of sclerostin in bone metabolism, study findings suggest that BCAA supplementation could serve as an adjunct therapy for conditions like osteoporosis, where elevated sclerostin levels contribute to bone loss." (PMID 41159395, 2025). "In patients with osteoporosis, sclerostin is a candidate biomarker due to its association with lower bone mineral content and bone density; therefore, a sclerostin inhibitor could be a promising therapy for bone-related disorders." (PMID 40806191, 2025). "Therefore, it is of interest to assess the diagnostic roleof serum sclerostin in patients with osteoporosis." (PMID 38352898, 2024). "Sclerostin was the focus of our investigation as it has been implicated in adult osteoporosis." (PMID 39062269, 2024). "Understanding the role of sclerostin in bone metabolism and the genetic mutation behind rare diseases such as sclerosteosis have helped in the development of new therapeutics for the treatment of common diseases such as osteoporosis." (PMID 35208525, 2022). "The question of whether anti-sclerostin antibodies might be effective in the treatment of OI or early-onset osteoporosis caused by heterozygous WNT1 mutations remains to be elucidated." (PMID 36004351, 2022). "We hypothesised that low IGF-1 and high sclerostin might act as markers for decreased bone formation in diabetic patients as they are associated with a higher risk of osteoporosis and fractures." (PMID 34690653, 2021). "It has been proposed by some authors that the paradoxical high serum levels of SOST in some patients with osteoporosis may be associated with a feedback loop in response to the loss of bone mass." (PMID 34497849, 2021). "Accordingly, an approach blocking Dkk1 as well as sclerostin might be the most effective strategy to counteract bone loss in cases of severe osteoporosis." (PMID 33479403, 2021). "Sclerostin monoclonal antibody romosozumab treatment significantly increases bone mineral density in postmenopausal women with low bone mineral density and reduces fracture risk in postmenopausal women with osteoporosis." (PMID 32733380, 2020).